HERC1 (HECT and RLD domain containing E3 ubiquitin protein ligase family member 1)
Diseases named in the same sentence as HERC1 in open-access papers (continued):
Sharing a sentence is not in itself a finding about the gene and the disease.
triple-negative breast carcinoma (1 paper, 2024). An invasive breast carcinoma which is negative for expression of estrogen receptor (ER), progesterone receptor (PR), and human epidermal growth factor receptor 2 (HER2). "HECT and RLD domain containing E3 ubiquitin protein ligase family member 1 (HERC1) promoted triple-negative breast cancer by regulating the ErbB pathway." (PMID 38654239, 2024).
tuberous sclerosis (1 paper, 2007). Hereditary disease characterized by seizures, intellectual disability, developmental delay, and skin and ocular lesions. "The HERC1 target protein TSC2 has been associated with the development of the hereditary disorder tuberous sclerosis complex (TSC)." (PMID 18047743, 2007).
tumor (13 papers, 2009 to 2026). "IL-6 neutralization or HERC1 inhibition sensitized organoids to 5-fluorouracil and cisplatin, and combined HERC1 knockdown with 5-FU markedly reduced tumor growth and increased apoptosis." (PMID 41965446, 2026). "We first injected MDA-MB-231 control or HERC1-silenced cells subcutaneously in the mammary fat pad of female mice and monitored tumor growth every 2–3 days." (PMID 33804079, 2021). "Overall and for the first time, we provide original evidence on the potential tumor-suppressing or -promoting properties, depending on the context, of HERC1 in myeloid related blood disorders." (PMID 33477751, 2021). "In vivo studies using immunocompromised mice demonstrated that HERC1 silencing decreased tumor growth and colonization into the lungs in experimental metastasis assays." (PMID 33804079, 2021). "In concordance with our results, it has been demonstrated that HERC1 protein shows increased expression in tumor cell lines and tumor breast cancer patients’ samples, compared to their respective normal counterpart." (PMID 33804079, 2021). "Our results indicate that HERC1 silencing decreases cell engraftment and tumor growth, as well as colonization into the lungs." (PMID 33804079, 2021). "Tumor growth curves analysis indicated that those generated from MDA-MB-231 HERC1-silenced cells were significantly less volumetric than the ones originated from control cells." (PMID 33804079, 2021). "After the selection procedure, we identified HERC1 as a candidate positive regulator of tumor cell migration and invasion." (PMID 33804079, 2021). "Gene expression of HERC1 has also been reported to be increased in human tumour cell lines and decreased in heroin users with a genetic variation of the opioid receptor." (PMID 20041218, 2009). "Therefore, the overactivation of ERK along with p38 that is triggered upon HERC1 deficiency could presumably lead to tumorigenesis and malignancy due to upregulation of the processes of cell proliferation and cell migration, pointing to HERC1 as a probable tumor suppressor protein." (PMID 36902336, 2023). "Furthermore, using animal models, our results indicate that HERC1 silencing affects primary tumor growth and lung colonization." (PMID 33804079, 2021). "Moreover, Kaplan–Meier analysis of tumor-free survival indicated that HERC1 silencing affected tumor development." (PMID 33804079, 2021). "Enhancing HERC1 ubiquitin ligase activity in this context could be an interesting approach to stop tumor progression in MAPK-dependent cancers." (PMID 32580485, 2020). "The search and identification of pharmaceutical stimulators of HERC1 activity could have great therapeutic potential in a variety of tumor types, including NSCLC, which is driven by the RAS oncogene most frequently mutated in human cancer." (PMID 30140388, 2018). "The HERC1 gene belongs to the HERC family that has ubiquitin ligase activity dependent on the protein substrates, HERC proteins may act as a tumor suppressor or oncoprotein in specific cancer types." (PMID 32724061, 2020). "In conclusion, we identified novel recurrently mutated genes in T-PLL, including PTPRC, regulating the JAK/STAT pathway, epigenetic regulators like PRDM2 and HERC1/2, and genes involved in DNA damage response and DNA repair like SAMHD1, which has most likely a tumor-suppressor function in T-PLL." (PMID 29352181, 2018).
cancer (11 papers, 2016 to 2023). A tumor composed of atypical neoplastic, often pleomorphic cells that invade other tissues. "Mutations of HERC1 gene or its deregulation have been associated with different pathologies, including neurological disorders and cancer." (PMID 33804079, 2021). "HERC1 binds to the M2 isoform of pyruvate kinase, which is typically found in proliferating tissues and cancer cells although the physiological role for this association has not been elucidated to date." (PMID 31447701, 2019). "The HERC family members are involved in cancer progression; in particular, HERC1 is involved in cell migration by regulating RAF/MKK3/p38 pathways." (PMID 37598287, 2023). "Similar to most E3 ubiquitin ligases, HERC1 has been shown to be a potential target for cancer therapy." (PMID 33841514, 2021). "In order to study the function of HERC1 in cell proliferation, we decided to perform a clonogenic assay in HERC1-depleted human cancer cells." (PMID 30140388, 2018). "HERC1 had been reported to regulate cell proliferation and ERK signaling by regulating C–RAF protein levels via ubiquitylation, and HERC mutations and expression are associated with cancer." (PMID 35889210, 2022). "Previous work suggests an important role of the E3 ubiquitin ligase HERC1 in cancer." (PMID 30140388, 2018). "According to the results of the analysis of malignant tumors, NCOA1, HERC1, HIPK3, MBNL1, hsa-let-7b-3p, hsa-miR-378a-5p, and hsa-miR-26a-5p were predictive or prognostic factors for malignant tumors." (PMID 33841514, 2021). "Within the down-regulated signaling pathways, there were ubiquitin-mediated proteolysis, mTOR signaling, pathways in cancer, RIG-like receptor signaling pathway with Herc1 and Traf6, Mapk1 and Rps6ka3, Ifg1r, Prkx, and Foxo1 as the core regulatory factors." (PMID 26900402, 2016). "To be sure that this regulation was not restricted to human cancer cells, we also demonstrated this increase in C-RAF protein amount by HERC1 knockdown in HEK-293T cells." (PMID 30140388, 2018).
cardiovascular disease (2 papers, 2023). "The increased expression of Fgf23 mRNA in osteocytes derived from Herc1-KO mice suggests an association between HERC1 loss-of-function and renal and cardiovascular disease." (PMID 36635269, 2023).
blood disorders (1 paper, 2021). "In the present study we examined the expression of the large HECT E3 Ubiquitin Ligase, HERC1, in blood disorders." (PMID 33477751, 2021).
infection (1 paper, 2017). The state of being infected such as from the introduction of a foreign agent such as serum, vaccine, antigenic substance or organism. "Of the genes participating in metal ion binding (MIB1, KAT6B, ITGA8, HBAC, KCNC1, and F13A), most were downregulated during the later stages of GCRV infection, whereas genes involved in protein ubiquitination (HERC1 and HERC4) were upregulated during the later stages of infection." (PMID 28906455, 2017). "HERC1 and HERC4 are probable E3 ubiquitin-protein ligases involved in ubiquitin-mediated protein degradation, and upregulation of these genes during the later stages of infection suggested that protein degradation occurred." (PMID 28906455, 2017).
metabolic disorders (1 paper, 2023). "In addition to these genes, variants were found in seven genes (ALDOB, MASP1, KIAA1109, TRAPPC4, SMARCAL1, HERC1, RRAS2) that were previously not reported in MPS but associated with other metabolic disorders." (PMID 37091798, 2023).
myopathy (1 paper, 2022). A disease of the muscle in which the muscle fibers do not function properly. "Forty-six candidate genes are prioritized by multiple approaches (42 for LST and 6 for MVPA; 2 overlap) and point to endocytosis (CNIH2, RAB1B, KLC2, PACS1, REPS1, DNM3, EXOC4), locomotion (CADM2, KLC2) and myopathy (MLF2, HERC1, KLC2, SIL1) as relevant pathways." (PMID 36071172, 2022).
neurodevelopmental disorder (1 paper, 2023). A behavioral and cognitive disorder with onset during the developmental period that involves impaired or aberrant development of intellectual, motor, or social functions. "Of interest, an association exists between biallelic pathogenic sequence variants in the HERC1 gene and the neurodevelopmental disorder MDFPMR syndrome (macrocephaly, dysmorphic facies, and psychomotor retardation)." (PMID 36635269, 2023).
HERC1 also shares sentences with these, for which no sentence is quoted: autism (4 papers); Macrocephaly (3); autism spectrum disorder (2); hepatoma (2); microcephaly (2); neurological diseases (2); T-cell acute lymphoblastic leukemia (2); acquired immunodeficiency syndrome (1); acute leukemia (1); acute myeloid leukemia (1); Alzheimer disease (1); behavioral disorders (1); brain malformations (1); cerebellar ataxia (1); Cerebellar atrophy (1); ciliopathy (1); depression (1); diabetes (1); esophageal cancer (1); Essential Thrombocytemia (1); gastric cancer (1); glioma (1); growth deficiency (1); intellectual impairment (1); lung adenocarcinoma (1); lysosomal storage disorders (1); mental illnesses (1); myeloid malignancies (1); non-melanoma skin carcinoma (1); osteoarthritis (1).
A further 6 diseases each share a sentence with HERC1 in 1 paper.